ALB (albumin)
Diseases named in the same sentence as ALB in open-access papers (continued):
Sharing a sentence is not in itself a finding about the gene and the disease.
breast carcinoma (continued). "The cytotoxic effects of albumin nanoparticles and DOX-loaded nanoparticles were first evaluated in vitro using the Raw264.7 murine macrophage cell line and MDA-MB-231 human breast cancer cells." (PMID 32906686, 2020). "We used fluorescent-labeled bovine serum albumin (BSA) as a positive control to optimize relevant transfection parameters, and proved that PKA enzymes through CRISPRMAX can be introduced into breast cancer cells." (PMID 33374889, 2020). "In this work, we have synthesized folic acid-decorated human serum albumin-coated Fe3O4 nanoparticles (C-MNP-HSA-FA) for synergistic delivery of 5-fluorouracil and curcumin for the treatment of breast cancer." (PMID 30565175, 2018). "Pre-treatment with CUR for 5 days prior to CIS treatment showed significant elevation of plasma albumin levels (p < 0.001), as compared to CIS treated breast cancer rats." (PMID 28420987, 2017). "Albumin coated silver nanoparticles (ASNPs) were synthesized, and their anti-cancerous effects were evaluated against MDA-MB 231, a human breast cancer cell line." (PMID 28701707, 2017). "A weak inverse association was also found between serum calcium levels, adjusted to serum albumin, and PMD in patients with primary breast cancer." (PMID 28464481, 2017). "In this work, a core-shell nanocarrier coated by cationic albumin was developed to simultaneously deliver miRNA-34a and docetaxel (DTX) into breast cancer cells for improved therapeutic effect." (PMID 28383524, 2017). "The polymer-drug conjugate, Abraxane, an albumin-bound paclitaxel drug formulation, was approved by the Food and Drug Administration, USA (FDA) in 2005 as a second-line treatment for the breast cancer." (PMID 24369011, 2013). "Background/Objectives: This study aimed to investigate the prognostic and predictive significance of the pretreatment neutrophil percentage-to-albumin ratio (NPAR) in patients with non-metastatic breast cancer." (PMID 41975711, 2026). "It haspreviously been shown that LDH is a poor prognosticfactor for metastatic and early breast cancer.No study has evaluated the LDH to albumin ratio(LAR) in breast cancer with NACT." (PMID 40386520, 2025). "A previous study on breast cancer cell line, MCF-7, demonstrated that albumin may affect cell proliferation by modulating the activation of autocrine growth regulatory factors (Laursen, Briand & Lykkesfeldt, 1990)." (PMID 40416620, 2025). "C-reactive protein (CRP)-to-albumin ratio (CAR) is an inflammatory and nutritional biomarker that has been well studied and reported to have an impact on the survival of patients with diverse types of cancer, but limitedly in breast cancer." (PMID 40416620, 2025). "The measurements of intracellular fluorescence of Cy5 covalently bound to albumin on nanoparticles after 1–24 h of incubation showed a folate-dependent accumulation in MCF-7 and MDA-MB-231 breast carcinoma cells, and this contrasting was detected by confocal microscopy." (PMID 40871005, 2025). "Regarding albumin and SUVmax, a positive correlation was noted in lung cancer and Hodgkin lymphoma, while a negative correlation was observed in breast cancer and non-Hodgkin lymphoma." (PMID 38957833, 2024). "Recently, we developed hybrid eumelanin–silver NPs (MelaSil_Ag) with photoacoustic properties, functionalised with human serum albumin (HSA), targeting breast cancer cells via HSA–SPARC interaction, to design DOX carriers (MelaSil_Ag-HSA@DOX NPs) for BC treatment." (PMID 38139203, 2023). "Here, FDA-approved macroaggregated albumin (MAA) particles were radiolabeled with Bismuth-212 (Bi-212-MAA) and evaluated using clonogenic and survival assays in vitro and using immune-competent mouse models of breast cancer." (PMID 37234203, 2023).
breast carcinoma (continued). "In this study, we developed and evaluated a novel nano-radio radiopharmaceutical, technetium-99m ([99mTc]Tc)-labeled trastuzumab (TRZ)-decorated methotrexate (MTX)-loaded human serum albumin (HSA) nanoparticles ([99mTc]-TRZ-MTX-HSA), for the diagnosis of breast cancer." (PMID 37754891, 2023). "Lugert and coworkers developed Ptx-functionalized super paramagnetic iron oxide (SPION) nanoparticles coated with lauric acid (LA) and human serum albumin (HSA; SPION LA-HSA-Ptx) and analyzed their efficacy in different breast cancer cell lines cultured in 2D and 3D." (PMID 35692756, 2022). "To date, less than 20 nanoformulations (liposome-based, albumin-bound, iron-based, etc.)have been approved by the Food and Drug Administration (FDA) or the European Medicines Agency (EMA) for the treatment of solid tumors, including breast cancer." (PMID 35335881, 2022). "Other factors related to more chemotherapy prescriptions shortly before death in ABC were younger age, higher albumin levels, greater disease burden, more prior lines of chemotherapy, and in this study we found HR−/HER2− breast cancer, and survival time <1 year as related factors." (PMID 34771434, 2021). "For example, the nanoparticle albumin-bound-paclitaxel is approved for treating breast cancer, non-small cell lung cancer, and pancreatic cancer." (PMID 34834551, 2021). "There are different forms of taxanes frequently used in clinical practice in breast cancer, including solvent-based paclitaxel (sb-PTX), docetaxel (a semi-synthetic analog of paclitaxel) and nanoparticle albumin-bound paclitaxel (nab-PTX), three of which are most frequently used worldwide." (PMID 34335933, 2021). "The pretreatment serum albumin-to-alkaline phosphatase ratio (AAPR) has been shown to be a prognostic predictor in several malignancies, but its predictive value for pCR in breast cancer is still unknown." (PMID 34692474, 2021). "Co-delivery of ATRA and paclitaxel using human serum albumin-bound (ATRA/PTX/HSA) NPs notably reduced MMP-2 and -9 levels in highly metastatic 4T1 mouse breast cancer cells and a murine 4T1 breast tumor model when compared with PTX-NPs or HSA-NPs loaded with single drugs." (PMID 33321708, 2020). "Finally, this work provides a new theranostic platform of mannosylated albumin–QD nanohybrids for targeted co-delivery of PMT and RSV to breast cancer cells." (PMID 30660179, 2019). "These randomized, two-period, crossover, clinical BE studies show that albumin-bound paclitaxel products (QL, HR, and ZDTQ) are bioequivalent to Abraxane® with a lower intra-cv and similar safety profiles of among Chinese breast cancer patients." (PMID 30559662, 2018). "Abraxane® or nanoparticle albumin-bound paclitaxel (NAB-paclitaxel) is a 130nm nano particle formulation originally developed by Abraxis BioScience, receiving regulatory approval in from the FDA 2005 and in 2008 from the EMA for the treatment of breast cancer." (PMID 29281685, 2017). "Based on the strong tendency for lymphatic metastasis in the initial stages of breast cancer progression in humans, we assessed whether the missing lymphatics around C3HBA tumors affected lymph flow, measuring washout of labeled albumin by optical imaging." (PMID 27329584, 2016). "In summary, the results of the present study suggest that preoperative albumin concentration predicts survival, independent of tumour-based factors, in patients undergoing potentially curative surgery for primary operable breast cancer." (PMID 17375036, 2007). "In the present study, albumin but not C-reactive protein was a significant, stage independent, predictor of survival in patients with primary operable breast cancer." (PMID 17375036, 2007). "For the detection of the breast cancer biomarker HER2, the researchers developed a light-responsive DNA origami structure, which incorporated a protein coating with targeted function on its surface and added a serum albumin camouflage agent to protect the DNA nanostructures." (PMID 40948789, 2025).
breast carcinoma (continued). "Fujii T's study investigated the relationship between serum levels of albumin and breast cancer, and demonstrated that low serum albumin levels were related to worse prognosis, but not a stand-alone prognostic indicator for the tumor microenvironment in breast cancer." (PMID 39512692, 2024). "This study aims to use three FDA-approved biological materials, human serum albumin, D-α-tocopherol succinate, and indocyanine green, to construct a novel biocompatible nanomaterial named HTI-NPs, exploring its effect in drug-resistant breast cancer (MCF-7/ADR cells)." (PMID 39507754, 2024). "We examined the relationship between albumin levels and mortality in various cancer types, including nonmelanoma skin cancer, prostate cancer, breast cancer, colorectal cancer, and melanoma, respectively, corroborating the overarching findings of this investigation." (PMID 38500655, 2024). "Two models of breast cancer (BT-474 and MDA-MB-231) were imaged longitudinally with diffusion-weighted MRI and dynamic contrast-enhanced MRI to quantify tumor cellularity and vascularity, respectively, during treatment with trastuzumab or albumin-bound paclitaxel." (PMID 32599906, 2020). "ASNPs increase ROS production in invasive breast cancer cell line of MDA-MB 231 after 24 h in comparison to SNPs and H2O2, which may be due to both higher levels of SNPs uptake to the cell and increasing oxidative effect of SNPs with albumin." (PMID 28701707, 2017). "Furthermore, other parameters that can be investigated using blood tests have not been evaluated, including C-reactive protein (CRP), lactate dehydrogenase (LDH), and albumin (Alb), which have been reported as prognostic predictors not only in breast cancer, but also in other types of cancer." (PMID 38965074, 2025). "However, the mechanisms underlying the prognostic significance of HALP for the OS and PFS in breast cancer are not yet fully elucidated, and the physiopathologic role of hemoglobin, albumin, lymphocyte, and platelet might explain this to some extent." (PMID 38956686, 2024). "This study synthesizes a novel self‐assembled multifunctional nanoprobe (NP) gadolinium–diethylenetriaminepentaacetic acid–human serum albumin@indocyanine green (ICG)–Bevacizumab to successfully improve the efficacy of fluorescence‐image‐guided surgery and radiotherapy for breast cancer (BC)." (PMID 36721054, 2023). "Moreover, the univariate analysis indicated that neither pretreatment ALB nor ALP could be used as a predictor for pCR in breast cancer patients." (PMID 34692474, 2021). "The lack of association between breast cancer risk and albumin in our study was consistent with findings of the AMORIS study, whereas a recent cohort study reported a weak inverse relationship, with the HRs being 0.71 (95% CI 0.51–0.99) for participants in the highest albumin quartile." (PMID 34041866, 2021). "Although women with breast cancer tend to have a greater proportion of their circulating oestradiol non-protein bound and albumin bound, and less SHBG-bound, than controls, it remains uncertain whether this has an aetiological role or is an effect of the tumour." (PMID 2310682, 1990). "In conclusion, metastatic versus non-metastatic breast cancer patients showed differences in terms of T-stage, N-stage, and levels of CA 15 − 3, CEA, albumin, ALP, NLR, and SII." (PMID 41398653, 2025). "In univariate Cox regression analysis, CRE, TBIL, LDH, UA, BUN, ALB, and CRP were correlated with the OS of breast cancer patients, while there is no statistical relationship between DBIL and OS." (PMID 34659642, 2021). "In 2005, Abraxane®, a 130 nm albumin-bound nanoparticle form of PTX, was approved by the Food and Drug Administration (FDA) as second-line therapy for breast cancer without corticosteroid premedication." (PMID 34225762, 2021).
hepatocellular carcinoma (310 papers, 1972 to 2026). A malignant tumor that arises from hepatocytes. "Modified albumin-bilirubin grade and platelet at cut-off 150,000/μL exhibited significant association with high-risk varices in patients with hepatocellular carcinoma." (PMID 40674357, 2025). "Wong LL reported that elevated alpha-fetoprotein levels, low levels of albumin and tumours > 5 cm in size were associated with increased 1-year mortality after hepatic resection for early-stage hepatocellular cancer in a retrospective study." (PMID 36494837, 2022). "We analyzed the association between the modified albumin–bilirubin (mALBI) grade and therapeutic efficacy of atezolizumab plus bevacizumab (Atezo+Bev) for the treatment of unresectable hepatocellular carcinoma (u‐HCC)." (PMID 35964253, 2022). "Hepatoma cell lines, such as HepG2 cells or others, are capable of spontaneous expansion and secretion of albumin in vitro, but, the risk of potential tumorigenicity cannot be ignored." (PMID 34858956, 2021). "First, targeted integration can lower serum albumin levels and albumin mutations have been observed in human hepatocellular carcinoma." (PMID 34713234, 2020). "We have revealed that a low recurrence rate of hepatocellular carcinoma (HCC) is associated with high serum albumin levels in patients; therefore, high levels of serum albumin are a major indicator of a favorable outcome." (PMID 24663086, 2014). "Thus, a nomogram was developed for evaluating the risk of hepatocellular carcinoma based on age, sex, serum albumin levels, and LSM." (PMID 38664813, 2024). "This study aims to evaluate the predictive value of the prognostic nutritional index (PNI) and albumin-bilirubin grade (ALBI) for the postoperative prognosis of hepatitis B virus-associated hepatocellular carcinoma (HBV-HCC) patients undergoing radical hepatectomy (RH)." (PMID 34272447, 2021). "Systemic inflammatory response represented by C-reactive protein to albumin ratio (CAR) was shown to be associated with long-term outcome in patients with hepatocellular carcinoma (HCC)." (PMID 39410928, 2024). "Background and Aim: A prediction model of hepatocellular carcinoma (HCC) risk in patients with chronic liver diseases, based on age, male sex, albumin-bilirubin, and platelets (aMAP), has been previously reported." (PMID 34422855, 2021). "Recent studies have indicated that the C-reactive protein/ albumin (CRP/Alb) ratio is associated with clinical outcomes in patients with hepatocellular carcinoma (HCC)." (PMID 26084991, 2015). "Many investigations have revealed that a low recurrence rate of hepatocellular carcinoma (HCC) is associated with high serum albumin levels in patients; therefore, high levels of serum albumin are a major indicator of a favorable prognosis." (PMID 24663086, 2014). "The Albumin-Bilirubin (ALBI) score was originally established to assess hepatic functional reserve in patients with hepatocellular carcinoma (HCC)." (PMID 41752736, 2026). "The albumin-bilirubin (ALBI) score was initially developed to assess liver function in patients with hepatocellular carcinoma." (PMID 42085717, 2026). "Hemodynamic stability and normal endothelial function maintain a transcapillary escape of albumin at 4% per hour, which is modified in cases of liver cirrhosis and hepatocellular carcinoma." (PMID 41379186, 2025). "The PALBI score, which integrates platelet count, serum albumin, and total bilirubin, was initially designed to evaluate hepatic function and forecast outcomes in individuals with hepatocellular carcinoma." (PMID 41210328, 2025). "This study evaluated the hepatoprotective effects and safety profile of donafenib combined with transarterial chemoembolization (TACE) in unresectable hepatocellular carcinoma (HCC) through analysis of albumin-bilirubin (ALBI) score modifications." (PMID 40951338, 2025).
hepatocellular carcinoma (continued). "Researchers have developed the albumin-to-bilirubin ratio (ALBI) as a tool to predict the survival of patients with hepatocellular carcinoma (HCC) who also have cirrhosis." (PMID 40929456, 2025). "The Albumin-Bilirubin Grade has gained importance as a tool for evaluating liver function and prognosis in patients with hepatocellular carcinoma." (PMID 38500655, 2024). "Concerning clinical and inflammation status, preoperative complete blood count, albumin, and pre-albumin have been widely studied as promising prognostic predictors in some tumors, like hepatocellular carcinoma, gastric cancer, and lung cancer." (PMID 39062127, 2024). "Herein, we purposed to determine the prognostic worthiness of systemic immune-inflammation index–albumin-bilirubin scores in patients receiving transarterial chemoembolization for unresectable hepatocellular carcinoma." (PMID 36620927, 2023). "The novel model combined CT–derived extracellular volume, measured future liver remnant ratio, and serum albumin outperforms the albumin–bilirubin score for predicting posthepatectomy liver failure in patients with resectable hepatocellular carcinoma." (PMID 37697217, 2023). "The prognostic value of albumin-to-alkaline phosphatase ratio (AAPR) in patients with hepatocellular carcinoma (HCC) remains controversial." (PMID 36720974, 2023). "The neo‐Glasgow prognostic score, based on C‐reactive protein level and albumin‐bilirubin grade, was developed as a new biomarker for hepatocellular carcinoma." (PMID 36484470, 2023). "The results presented in this study demonstrate the successful synthesis and preparation of PEI-Fe3O4/pYr-ads-8-5HRE-cfosp-IFNG albumin nanospheres for targeted delivery of IFNG to hepatoma cells." (PMID 37091158, 2023). "Consistent with mouse data, human hepatoma cells treated with bovine serum albumin-oleic acid (BSA-OA) tended to increase PTP4A1 mRNA levels compared to controls." (PMID 36793871, 2023). "The therapeutic effect of PEI-Fe3O4/pYr-ads-8-5HRE-cfosp-IFNG albumin nanospheres on hepatocellular carcinoma was investigated by cell and animal experiments." (PMID 37091158, 2023). "The results suggested that the targeted delivery of IFNG by the PEI-Fe3O4/pYr-ads-8-5HRE-cfosp-IFNG albumin nanospheres was effective in inhibiting the proliferation of hepatoma cells." (PMID 37091158, 2023). "PII is derived from ALB and lymphocytes, which are indicators of nutritional status and systemic inflammation in hepatocellular carcinoma and pancreatic cancer." (PMID 37699964, 2023). "Our experiments demonstrated that the PEI-Fe3O4/pYr-ads-8-5HRE-cfosp-IFNG albumin nanospheres system is a comprehensive treatment method for hepatoma, which can effectively combine immune genre therapy with hyperthermia." (PMID 37091158, 2023). "To test this, we treated human hepatoma cells, HepG2, with different concentrations of palmitate bound to fatty acid–free bovine serum albumin (BSA) for 24 h." (PMID 36690274, 2023). "Hydro-methanolic extracts from Halocnemum strobilaceum and Suaeda fruticosa have been investigated for the inhibition of bacterial growth, the protection of proteins (albumin) from denaturation, and cytotoxicity to hepatocellular carcinomas (Huh-7 and HepG2)." (PMID 37110814, 2023). "Recently, the neo‐Glasgow prognostic score (GPS), a composite biomarker determined by the C‐reactive protein level and albumin–bilirubin grade, was developed to predict outcomes in hepatocellular carcinoma (HCC) patients who undergo hepatic resection." (PMID 36484470, 2023). "Numerous studies have confirmed the prognostic value of ALB in different tumors, especially hepatocellular carcinoma." (PMID 38041022, 2023).